HIF1A (hypoxia inducible factor 1 subunit alpha)
Diseases named in the same sentence as HIF1A in open-access papers (continued):
Sharing a sentence is not in itself a finding about the gene and the disease.
hepatocellular carcinoma (597 papers, 2008 to 2026). A malignant tumor that arises from hepatocytes. "The promotion of hepatocellular carcinoma metastasis was also facilitated by the activation of the HIF1α/ZEB1 axis through CCL5 derived from cancer‐associated fibroblasts." (PMID 40062588, 2025). "In the context of hepatocellular carcinoma, reduced expression of HIF-1α is associated with diminished lipid metabolic reprogramming, partly due to the suppression of key metabolic enzymes." (PMID 41333208, 2025). "HIF-1α is closely associated with the progression and metastasis of cancers, such as gastric cancer, hepatocellular carcinoma and pancreatic cancer." (PMID 35819532, 2022). "In patients with hepatocellular carcinoma, the increased HIF-1α was associated with lymph node invasion and patient mortality." (PMID 35396948, 2022). "It was reported that chemoresistance is associated with a high level of HIF-1α expression in many cancer types including ovarian cancer, hepatocellular carcinoma, glioblastoma, and colorectal cancer." (PMID 34680470, 2021). "Hypoxia-inducible factor-1α (HIF-1α) promotes oncogenesis in hepatocellular carcinoma and is functionally linked to cell proliferation, chemoresistance, metastasis and angiogenesis." (PMID 34540836, 2021). "In human hepatoma cells, HIF-1α has been found to cause repression of Myc, resulting in decreased expression of PGC-1β, which led to the inhibition of mitochondrial fatty acid β-oxidation." (PMID 34572020, 2021). "Another study demonstrated that linc-RoR is a hypoxia-responsive lncRNA that is functionally linked to hypoxia signaling in hepatocellular carcinoma through a miR-145/HIF-1α signaling module." (PMID 33407675, 2021). "Our results demonstrate that MOF expression is negatively associated with HIF-1α expression in hepatocellular carcinoma tissues and in response to chloride-mimicked hypoxia in hepatocellular carcinoma cell lines." (PMID 34540836, 2021). "For example, TIMP2 (tissue inhibitor of metalloproteinases 2) blockade by HIF-1α/miR-210/HIF-3α feed circuit often plays a significantly role in regulating hepatocellular carcinoma (HCC) metastasis, which is regard as associated with poor prognostic effects." (PMID 33109235, 2020). "Herein, we report that FABP5 and HIF-1α were upregulated in hepatocellular carcinoma (HCC) tissues and their expression levels were associated with poor prognosis." (PMID 33128030, 2020). "A recent study proved that co-expression of IL-8and HIF-1α is associated with metastasis and poor prognosis in hepatocellular carcinoma." (PMID 30258464, 2018). "Recent studies demonstrated that HIF-1α expression is regulated by miRNAs and SNP rs2057482 in HIF1A gene is significantly associated with clinical outcomes of hepatocellular carcinoma patients after surgery." (PMID 26872370, 2016). "Our studies show that HCV infection and the viral encoded glycoproteins reduce hepatoma polarity and increase cell migration by stabilizing HIF-1α expression and upregulating downstream effectors, VEGF and TGFβ." (PMID 22178269, 2012). "For instance, high expression of HIF-1α has been associated with unfavorable responses to treatment in hepatocellular carcinoma undergoing local ablation therapies, as well as in oral cancer and locally advanced head and neck squamous cell carcinomas treated with cisplatin and radiation therapy." (PMID 39757165, 2025). "Hypoxia also promotes remodeling of the actin cytoskeleton and cancer cell motility through the activation of the RhoA/Rho-associated protein kinase (ROCK) signaling pathway by HIF-1α, which leads to increased invasion and migration of hepatocellular carcinoma (HCC) cells in vitro and in vivo." (PMID 37490147, 2023). "In addition, under hypoxic stress, YAP can associate with the HIF-1α protein and maintain its stability to enhance glycolysis in hepatocellular carcinoma." (PMID 37041150, 2023).
hepatocellular carcinoma (continued). "Thus, enhanced glycolysis in hepatocellular carcinoma cells is largely dependent on NF-κB/HIF-1α activation caused by hypoxia." (PMID 35178457, 2022). "Patients who expressed high levels of HIF-1α were associated with a worse outcome, with a pooled risk for overall survival (RR = 1.508) that was similar to that obtained in a recently published study on hepatocellular carcinoma (HR = 1.65)." (PMID 24647137, 2014). "SLC7A11 expression is positively associated with HIF-1α in human hepatocellular carcinoma (HCC) tissues." (PMID 35624785, 2022). "Besides, it is revealed that the overexpression of HIF1α is associated with the upregulated HP under the hypoxia condition in human hepatoma cells, suggesting that HP may be secreted by nearby cancer cells under the hypoxia." (PMID 31217907, 2019). "Importantly in the past fewyears, hif-1α has been implicated in the development of a range ofliver pathologies, such as liver fibrosis, activation of the immune system,hepatocellular carcinoma, and others, in humans, as well as in rodents (Nath and Szabo, 2012, Semenza, 2012)." (PMID 28486571, 2017). "In vitro and in vivo experiments have also confirmed that the downregulation of IL-6 or MCP1 (CCL2) in hypoxia inhibits HIF-1α expression in hepatocellular carcinoma." (PMID 40430040, 2025). "The relevance of hypoxia in response to metformin is highlighted by its ability to reduce the volume and weight of hepatocellular carcinoma tumors by decreasing the expression of HIF-1α, VEGF, and MMOLP-2." (PMID 40507826, 2025). "YTHDF1, induced by HIF-1α, promotes hypoxia-induced autophagy and hepatocellular carcinoma malignancy through m6A-modified ATG2A and ATG14 dependency." (PMID 40251202, 2025). "This study examined the effects of combining the HIF-1α inhibitor YC-1 with the KD formula KetoCal® on hypoxic hepatocellular carcinoma (HCC) cells." (PMID 41465202, 2025). "ABCF1 K430la mediates its nuclear translocation, upregulates KDM3A expression, and enhances H3K9me2 demethylation, activating the HIF1A pathway to promote hepatocellular carcinoma progression." (PMID 40994548, 2025). "High HIF-1α and CXCL8 are associated with the development of hepatocellular carcinoma and metastasis." (PMID 40076892, 2025). "lncRNA FRMD6-AS1 is significantly upregulated in hepatocellular carcinoma tissues and cells, regulating the stability of HIF-1α through direct interaction with the de-SUMOylating enzyme SENP1." (PMID 40861273, 2025). "Our data shows that it’s abundantly expressed and highly active in the ventral neural tube, and it also has been shown to bind to Hif1a mRNA in hepatocellular carcinoma cells." (PMID 41446274, 2025). "In contrast, ERK and JNK are responsible for mediating lipopolysaccharide-stimulated HIF-1α mRNA, which is induced in human monocytes/macrophages and hepatoma cells, respectively." (PMID 39757165, 2025). "USP2-AS1 enhances YBX1-HIF1α mRNA binding under hypoxia, increasing HIF1α protein levels and hepatocellular carcinoma growth." (PMID 40799245, 2025). "In the remaining analysed cancers, a higher WWOX/HIF1A expression ratio also allowed for determining the prognosis; in brain tumours and hepatocellular carcinoma, it clearly correlated with better survival." (PMID 41007296, 2025). "Carvacrol (15 mg/kg) combined with sorafenib modulated HIF‐1α/STAT3/FGL1 pathway in a hepatocellular carcinoma (HCC) murine model." (PMID 40964147, 2025). "Hydroxyproline inhibits prolyl hydroxylases, stabilizing HIF‐1α and promoting cancer cell survival, notably in hepatocellular carcinoma (HCC)." (PMID 41200384, 2025).
hepatocellular carcinoma (continued). "The 3D organoid model provides a physiologically relevant platform for replicating HIF-1α–regulated metabolic processes in hepatocellular carcinoma (HCC)." (PMID 41002858, 2025). "The flavonoid kaempferol deactivates HIF‐1α signaling by promoting its relocation from the nucleus to the cytoplasm in hypoxic human hepatoma cells, thereby inhibiting VEGF transcription, which suppressed angiogenesis and malignant transformation." (PMID 40781971, 2025). "This USP2-AS1/HIF1α positive feedback loop facilitates migration, invasion, and the development of drug resistance in hepatocellular carcinoma cells." (PMID 40861273, 2025). "SENP1 increases the sphere formation ability of hepatocellular carcinoma cells through deSUMOylating HIF-1α." (PMID 38389923, 2024). "The study found that protein expression of NRF2 was unaffected by inhibiting HIF-1α in HepG2 human hepatoma cells." (PMID 39286246, 2024). "The inhibition of these key enzymes in aerobic glycolysis also suppressed expression of nuclear transcription factors such as HIF-1α and β-catenin, ultimately inhibiting the proliferation of hepatocellular carcinoma cells." (PMID 38841361, 2024). "Meanwhile, sorafenib, regorafenib, and axitinib have been documented to suppress the HIF‐1α/VEGFA pathway in hepatoma." (PMID 39359691, 2024). "The pharmacological inhibition or gene knockdown of SIRT1 upregulated VLDLR protein levels in the human Huh-7 hepatoma cell line, with this increase abolished by the pharmacological inhibition of HIF-1α." (PMID 38807218, 2024). "In hepatocellular carcinoma (HepG2) cells, Celastrol at 2 and 4 μg/mL inhibited nuclear HIF-1-α protein expression through western blotting and Celastrol also inhibited HIF-1-α mRNA dose-dependently in HepG2 and A549 cells." (PMID 38338464, 2024). "lncRNA (UBE2CP3) enhances VEGFAsecretion and promotes angiogenesis in HCC cells by activating ERK1/2/HIF-1α/VEGFAsignaling in hepatocellular carcinoma." (PMID 39682093, 2024). "Taking HIF-1α as an example, its levels in hepatocellular carcinoma (HCC) have been studied to determine the effectiveness of transarterial chemoembolization (TACE) treatment." (PMID 39275392, 2024). "Fucosyltransferase 11 (FUT11), activated by transcription factor HIF1α, advanced the proliferation and mobility of hepatocellular carcinoma cells." (PMID 38270646, 2024). "For example, HIF-1α was found to not only promote the glycolytic process but also enhance the expression of YTHDF1/2 in hepatocellular carcinoma (HCC) and lung squamous cell carcinoma (LUSC), respectively, leading to cancer cell spread." (PMID 39033180, 2024). "MIAT and HIF-1α were highly expressed, and miR-203a was lowly expressed in hypoxia-stimulated hepatocellular carcinoma cells after TACE." (PMID 39204162, 2024). "There are other EMT pathways, such as Wnt/β-catenin, which can increase hypoxia-induced EMT by HIF-1α signaling in hepatocellular carcinoma and the hedgehog pathway, in which HIF-1α mediates EMT and invasion in pancreatic cells." (PMID 38791951, 2024). "Hypoxia in hepatocellular carcinoma can induce NK cells to upregulate HIF-1α, which then alters the expression of glycolytic enzymes, metabolite transporters and enzymes involved in biosynthesis, thereby affecting the metabolism of immune cells." (PMID 38334792, 2024). "Knockdown of HOTAIR in hypoxia-treated hepatocellular carcinoma cells inhibits glycolysis via regulation of miR-130a-3p and HIF1A, a novel glycolysis mechanism in hepatocellular carcinoma." (PMID 39167430, 2024). "ALDH18A1 affects the stability of HIF1α by regulating the level of proline metabolism and thereby regulates the proliferation of hepatocellular carcinoma cells." (PMID 39051546, 2024). "On the basis of the previous findings, we deduced that the high expression of HIF-1α in hepatocellular carcinoma cells is positively correlated with STAT3 and VEGF." (PMID 37333486, 2023).
hepatocellular carcinoma (continued). "Insufficient RFA has been reported to trigger angiogenesis and proliferation in residual hepatocellular carcinoma via upregulation of HIF-1α." (PMID 37948404, 2023). "This phenomenon was suppressed when FABP5 or HIF-1α were silenced, indicating that the FABP5/HIF-1α axis is involved in OA-driven hepatocellular carcinoma cell growth." (PMID 37373069, 2023). "Based on the previous findings, it is presumed that the high expression of HIF-1α in hepatocellular carcinoma tissues is positively correlated with STAT3 and VEGF." (PMID 37333486, 2023). "At present, few studies confirmed the effect of curcumin on the HIF-1α/STAT3/VEGF signal transduction pathway against hepatocellular carcinoma." (PMID 37333486, 2023). "HIF-1α can activate Wnt/β-catenin signaling via regulating BCL9 expression in hepatocellular carcinoma." (PMID 38031108, 2023). "TAMs secrete more IL-1β under moderate hypoxic conditions because of the increased stability of HIF-1α, which induces necrotic debris in hepatocellular carcinoma cells." (PMID 37491279, 2023). "The binding of HGF to its receptor c-Met can trigger Hif1a expression in PI3K-dependent mode in HepG2 hepatoma cells." (PMID 37842051, 2023). "Studies also showed that the expression of HIF-1α was significantly correlated with the progression of hepatocellular carcinomas." (PMID 37333486, 2023). "Our results indicate that curcumin suppressed hepatocellular carcinoma cell migration by disturbing the cell cycle and transduction signal pathways HIF-1α/STAT3/VEGF." (PMID 37333486, 2023). "It has been shown that YTHDF1 expression upregulated in a HIF-1α-dependent manner by promoting transcription in human hepatocellular carcinoma." (PMID 36675257, 2023). "In hypoxic hepatoma cells and xenografted models, ginsenoside CK in a dose of 20–60 μM down-regulated the protein level of HIF1α, glycolysis, GLUT1, glycolytic enzymes HK2, and LDHA, as well as PDK1." (PMID 38001865, 2023). "The pesticide triflumuron, via hypoxia-induced factor 1α (HIF-1α), induces, in hepatocellular carcinoma (HepG2) cells, migration, invasion, and metastasis." (PMID 36908412, 2023). "IL-1β produced by inflammatory macrophages increases PD-L1, as well as HIF-1α-dependent CSF-1 expression in hepatoma cells, facilitating TAM accumulation." (PMID 36845555, 2023). "In a previous study, it was reported that hepatitis C virus infection increased ATX expression in hepatocellular carcinoma cells via HIF-1α." (PMID 37108194, 2023). "More recently, DKC1 was found to promote proliferation, survival, invasion and metastasis of colorectal and hepatocellular cancer cells by enhancing HIF-1α expression and antioxidative effect, respectively." (PMID 37434223, 2023). "It has already been mentioned in many studies that MST1 and YAP are involved in the regulation of HIF-1α in granulocyte progenitor cells, chondrocytes, and hepatocellular carcinoma cells." (PMID 38274792, 2023). "It suggests that autologous blood transfusion can increase the expression of HIF‐1α during hepatocellular carcinoma surgery." (PMID 37038623, 2023). "Increasing stiffness of ECM enhances M2 polarization and HIF-1α-induced LOXL2 expression via β5 integrin/FAK/MEK/ERK pathway of macrophage in hepatoma." (PMID 36906534, 2023). "The deubiquitination activity of USP14 induces proliferation, invasion, migration, and vascular mimicry of hepatocellular carcinoma via maintenance of HIF1-α stability." (PMID 37046655, 2023). "The data suggest that it is involved in suppressing hepatocellular carcinoma invasion through HIF-1α expression in hypoxic tumor microenvironments." (PMID 36983834, 2023). "EGFR-induced phosphorylation of different pathways contributed to HIF-1α signaling loop, regulated glucose metabolism in pancreatic cancer, and promoted hepatocellular carcinoma progression." (PMID 36154925, 2023).
hepatocellular carcinoma (continued). "In various types of tumors, such as hepatocellular carcinoma, neuroblastoma, and lung cancer, HIF-1α inhibition re-sensitizes cells to drug treatment; therefore, it is considered a valid target to reduce drug resistance induced by reverse hypoxia." (PMID 38026933, 2023). "Hypoxic stress promotes YAP binding to HIF‐1α in the nucleus and sustains HIF‐1α protein stability to promote glycolysis in hepatocellular carcinoma cells." (PMID 36757143, 2023). "Hepatocellular carcinoma cells express AM and its receptor and, under hypoxic conditions, favor AM expression; in addition, AM mRNA, HIF-1α and VEGF levels were increased under the same conditions in human hepatocellular carcinoma cell lines." (PMID 36980580, 2023). "HSP90 expression was observed to exhibit a positive correlation with the expression of HIF-1α protein in tissues of hepatocellular carcinoma." (PMID 38022589, 2023). "Melatonin can inhibit the mTORC1/p70S6K/RP-S6 pathway to downregulate HIF-1α protein production and diminish cytoprotective HIF-1α-mitophagy expression in hepatocellular carcinoma, hence increasing sorafenib sensitivity." (PMID 37460927, 2023). "Here we found that CDK5 and HIF1α can positively regulate DHHC7 expression and there is a positive feedback loop formed by DHHC7, STAT3, and HIF1α, which contributes to the malignancy of hepatic carcinoma." (PMID 38051779, 2023). "It cannot be ruled out that PFKFB3 protein is induced at later stages of hypoxia, since it was reported that metformin suppressed PFKFB3 expression by preventing HIF-1α accumulation in hepatoma cells, thereby inhibiting glycolysis and proliferation." (PMID 35072776, 2022). "Recent studies have revealed that HIF-1α expression is upregulated in solid tumors such as colorectal carcinoma, hepatocellular carcinoma, and thyroid cancer." (PMID 36329448, 2022). "Compared with parent cells, hepatoma cells treated with SHS increase the expression of HIF-1α and VEGF, and enhance angiogenesis, which can be eliminated by Avastin." (PMID 36081558, 2022). "Another study has revealed that neuronal PAS domain protein 2 promotes aerobic glycolysis of hepatocellular carcinoma cells through the transcriptional upregulation of HIF-1α, thus promoting PGC-1α downregulation." (PMID 35896535, 2022). "Caffeic acid attenuated hepatocellular carcinoma cells’ angiogenesis by reducing JNK-1-mediated HIF-1α stabilization." (PMID 35235611, 2022). "In hepatocellular carcinoma, HIF-1α promotes the expression of YTHDF1 by binding to the promoter of YTHDF1, and then combines with ATG2A and ATG14 by m6A modification to promote their translation and malignant progression of cancer." (PMID 35022030, 2022). "For example, N1-guanyl-1,7-diaminoheptane (GC7), an inhibitor of eIF5A2, reduced doxorubicin resistance in hepatocellular carcinoma cells by reversing hypoxia-induced EMT through the HIF-1α signaling pathway." (PMID 35931669, 2022). "In hepatocellular carcinoma cells, for instance, the hypoxia-inducible factor-1 alpha (HIF-1α) directly controls STIM1 transcription and contributes to SOCE." (PMID 36142596, 2022). "Erdem and colleagues demonstrated a protective role of adipose tissue macrophages (ATM) in an intercrossed transgenic murine model that genetically induces hepatocellular carcinoma (HCC) and also presents a myeloid-specific deficiency in hypoxia-inducible factor 1α (HIF1α)." (PMID 36033972, 2022). "Clinically, we detected HIF1α in hepatocellular carcinoma tissues and matching paracancerous tissues, and almost all samples exhibited higher HIF1α expression in tumor tissues compared with paracancerous tissues." (PMID 35589690, 2022). "In hepatocellular carcinoma cells, hypoxia-inducible factor-1alpha (HIF-1α) and hypoxia-inducible factor-2alpha (HIF-2α) bind directly to the PIM2 promoter and induce PIM2 expression." (PMID 35892829, 2022).